CD44 (CD44 molecule (IN blood group))
Diseases named in the same sentence as CD44 in open-access papers (continued):
Sharing a sentence is not in itself a finding about the gene and the disease.
tumor (continued). "The EAC cell line OE19 built tumor spheres, when cultured in serum-free medium, with increased expression levels of CD44 and they were more resistant to radiotherapy as the parent OE19 clone." (PMID 32560537, 2020). "HA-conjugated paclitaxel has been shown to selectively bind CD44+ tumor cells and block cancer cell line proliferation in vitro of numerous cancer types, including ovarian." (PMID 33335857, 2020). "CD44 plays an important role in tumor initiation and metastasis and seems to be involved in sphere formation in primary SCLC lines." (PMID 31446534, 2020). "In order to identify the exact stage of the blockade in DN-T-cell transition, we next examined the status of the DN2a (CD25+CD44+c-Kithigh) and DN2b (CD25+CD44+c-Kitlow) subpopulations within the tumor-conditioned thymi." (PMID 32582141, 2020). "PPARγ expression was dramatically upregulated in GBM tumors compared to the corresponding normal tissues in the two patients, and the tumor tissues showed CD44-positive expression, indicating an MES subtype." (PMID 32280134, 2020). "This was found to be associated with an increase in MHC class I, PD-L1, and CD54 expression and a reduction in CD44 levels on tumor cells." (PMID 32391048, 2020). "In an orthotopic mouse model of OS, injection with CD44 overexpressing OS cells resulted in increased primary tumor formation and lung metastasis, which was dependent on the HA to CD44 interaction." (PMID 32887645, 2020). "Another marker is CD44, a prominent stem cell marker located in the basal cell layer of the normal and tumor urothelium." (PMID 31963556, 2020). "A population of CD44+ tumor cells exists in HNSCC, which are considered “cancer stem cells” and are associated with tumorigenesis and resistance to chemo- or radiotherapy." (PMID 33072064, 2020). "CD44 has been shown to be involved in tumor growth and metastasis and has also been reported as a cancer stem cell (CSC) marker in head and neck squamous cell cancer (HNSCC)." (PMID 32597160, 2020). "Upregulation of CD44 confers tumorigenicity, metastatic capacity, and drug resistance to primary tumor cells as well as CTCs." (PMID 32984308, 2020). "ALDH/CD44+/PD-L1+ CSCs were found in close contact with PD-1+ T cells both in murine and human tumor samples, suggesting a direct effect of CSCs in immune control." (PMID 33123122, 2020). "The expression of CD44, CD44v6, and CD44v8-10 seems to increase at higher stages compared with stage I tumor." (PMID 32039729, 2020). "Altogether, CD44 is involved at multiple steps of tumor progression and its inhibition appears as a promising alternative for tumor-ECM targeting therapies." (PMID 32793493, 2020). "Loss of CD44 in MDA-MB-231 cells led to a decrease in the total number of lung lesions, as well as the percent area colonized by tumor cells." (PMID 32455980, 2020). "For instance, the expression of CD44, a Wnt target gene, can be detected in primary and metastatic malignancies, where tumor cells with elevated levels of CD44 have been shown to behave as CSCs." (PMID 33126517, 2020). "The major component of tumor stromal cells is cancer-associated fibroblasts (CAFs), which positively express CD90 and CD44." (PMID 32466488, 2020). "In one case, CD44+CD24- cell subsets were detected only in the primary tumor, and in other cases, only in the blood." (PMID 32316333, 2020). "MMP9 gene silencing is shown to change the expression of CD44 and significantly decreases migration and invasion of tumour cells." (PMID 32445177, 2020). "These suggest that tumor accumulation of anti-CD44-mAb-IR700 1 day after injection as a target antigen is predicted to be lower in MOC1 tumors and direct cell killing by CD44-targeted PIT is expected to be less efficient compared with MC38-luc or LL/2 tumors." (PMID 32937841, 2020).
tumor (continued). "Up to now, two major types of factors have been found to be involved in RCC metastasis: one is tumour angiogenesis factors that can promote metastasis, such as MMPs and CD44, and the other is tumour suppressors, such as VHL and PTEN." (PMID 32209138, 2020). "More specifically, we noticed a dramatic reduction in early tumor formation using the Hs578T orthotopic transplant model when CD44 was deleted from cancer cells." (PMID 32455980, 2020). "Immunodetection of CD44 isoforms like CD44v9 in tumor tissue is almost exclusively performed by using specific monoclonal antibodies." (PMID 31973075, 2020). "This review aims to encapsulate the structure of CD44 gene and protein, outline the roles which CD44 plays in tumor initiation, progression and therapy-resistance, and also highlight the perspectives for CD44-targeted therapy." (PMID 33303029, 2020). "Several studies identified STAT3 as an important interaction partner for CD44 in promoting tumor properties across various cancer models, including ovarian." (PMID 33335857, 2020). "CD44 is a stem cell marker and appears to have a dual nature regarding tumor progression and metastasis." (PMID 33087801, 2020). "ALDH+CD44+ cells displayed enhanced tumour-initiating activity, as evident from the increased tumour incidence and significantly higher estimated tumour-initiating cell frequency." (PMID 32390009, 2020). "CD44 is highly expressed in most cancer cells and its cross-linking pattern is closely related to tumor migration and invasion." (PMID 33292278, 2020). "Initially, we used flow cytometry to show that the immune checkpoint receptor Programmed Death Receptor 1 (PD-1) was expressed on activated (CD44+) CD8 T-cells in all tumor types." (PMID 31959281, 2020). "Based on these studies, CD44 and STAT3 have overlapping functions within tumor-associated regulatory T cells." (PMID 33335857, 2020). "The downregulation of LRP was important during the prevention of migration, because LRP played an important role with CD44 in adhesion mechanisms in tumor progression." (PMID 32182839, 2020). "During the study of stem characteristics in tumor cells, it is necessary to use at least these three markers (CD44/CD24, CD133, and ALDH1)." (PMID 32316333, 2020). "An in vitro single-cell cloning assay revealed that CD44+ cells have a high self-renewal ability and the same clonogenic capacity as the parental tumor." (PMID 31963556, 2020). "IHC assay of CD44 expression in frozen sections from mouse tumour revealed that tumour stemness decreased in tumours overexpressing DAXX." (PMID 32203224, 2020). "It is known that migration of the breast CSC population (CD44+ CD24-/low) gradually increases with tumor stage progression and that PKCλ KD decreases the migration potential of multiple TNBC cell lines." (PMID 32658903, 2020). "The CD44+CD24−/low phenotype is associated with breast cancer 1 (BRCA1) mutational status and basal-like tumor status." (PMID 32316333, 2020). "When the analysis was restricted to the luminal ER+ tumours, high BMI1 expression was associated with low expression of ALDH1A1 (P = 0.025), ALDH1A3 (P = 0.026), CD133 (P = 0.038), CD44 (P = 0.0001), CD24 (P = 0.004) and SOX10 (0.0006)." (PMID 32524353, 2020). "Re-challenge of these PI3KδKI mice, which previously rejected TCL1-leukemia, with tumor cells resulted again in tumor rejection and expansion of CD44+ effector/memory CD4+ as well as CD8+ T-cells." (PMID 33552053, 2020). "The expression of CD44 proteins in tumor tissues and serum samples from NSCLC has been found to be significantly associated with clinicopathological factors including T stage, N stage, and pathological stage." (PMID 32344833, 2020). "Next, we evaluated tumor progression and survival after the combination of CD44-targeted NIR-PIT and short-term administration of an anti-PD1 immune checkpoint inhibitor (ICI) to further activate CD8+ T cells." (PMID 33322807, 2020).
tumor (continued). "Even after incubation with IL-6, the concentration of EpCam+CD44+CD24– tumor stem cells was 1.33 times higher in patient St23784/17 than patient Ti41749/17." (PMID 32523653, 2020). "Our immunohistochemical analysis of CD44 expression in EOC patients indicated CD44 involvement in a functional crosstalk between tumor and surrounding stroma." (PMID 33335857, 2020). "IHC staining of tumor sections revealed stronger cancer stemness markers (anti‐CD44, Twist, and Bmi1) and higher proliferative activity (anti‐Ki67) in tumor lesions stably expressing WT or Q311E." (PMID 32979859, 2020). "The co-expression of CD44 with the c-Kit receptor CD117 was shown to define an ovarian subpopulation with tumor-initiating capacity." (PMID 32257947, 2020). "SRGN in the tumor microenvironment binds to tumor cell surface CD44 via its GAGs, and facilitates cytoskeleton reorganization and Src-mediated focal adhesion turnover, leading to increased cell migration." (PMID 31898491, 2020). "In vitro and in vivo CD44 expression in all three tumor models and cytotoxic effects of CD44 targeted NIR-PIT have been previously reported." (PMID 32927646, 2020). "As is shown in the multi-colour immunofluorescence staining analysis of 135 GC tissues, ~90% of tissues show that NECTIN2, CEACAM1, HMGB1, SIGLEC6 and CD15 were expressed in tumour cells, and CD44 was expressed in tumour cells in about 70% of tissues." (PMID 33311518, 2020). "In particular, binding to CD44, which is a transmembrane glycoprotein mediating lots of important activities of tumour cells, has been reported." (PMID 32770099, 2020). "Tumor growth was significantly inhibited in the CD44-targeted NIR-PIT group compared with all other groups at day 29 (p < 0.0001)." (PMID 33322807, 2020). "For instance, tumor progression is decelerated and apoptosis is triggered in leukemic stem cells by an anti-CD44 mAb." (PMID 32211043, 2020). "Even though many receptors are able to bind the ECM, three are mainly described in tumor progression (CD44, integrins and DDRs)." (PMID 32984031, 2020). "Matching cell phenotypes in the primary tumor and the blood allowed us to assume that stemlike CD44+ tumor cells have decreased intravasation capacity and CTC generation regardless of N-cadherin expression." (PMID 32316333, 2020). "CD44 is a type 1 transmembrane cell-surface glycoprotein with tumor promoting functions in many types of cancer cells." (PMID 32193421, 2020). "Of note, the expression of CD44 is significantly higher in metastatic and recurrent OS patient tumor specimens compared to primary tumor tissues." (PMID 32887645, 2020). "It was found that CD44 positive tumor cells have a series of stem cell characteristics, such as strong proliferation, invasion, anti-apoptosis, and stable passage." (PMID 32520954, 2020). "The percentages of tumor-infiltrating CD45+CD3+ cells as well as tumor-infiltrating CD8+CD44+ T cells gated from CD45+CD3+ cells were quite low in this study." (PMID 32733437, 2020). "GPI-APs such as the folate receptor (FR) and CD44 have also been frequently targeted due to their important roles in tumor growth and migration." (PMID 32932957, 2020). "In aggressive BC, the combination of anti-human CD44 monoclonal antibody with doxorubicin and cyclophosphamide using NPs has been used to prevent tumor recurrence." (PMID 33584277, 2020). "Only cells expressing CD44 on the surface persist after chemotherapy treatment and are able to rebuild the tumor afterwards." (PMID 33335857, 2020). "The results also showed that the combination of sorafenib and GANT61 exerted the most potent effect in inhibiting tumor formation, especially for CD44-positive HCC cells." (PMID 31992334, 2020). "We employed CD44 as a tumor target, which is a well-known marker of cancer stem cells and is expressed on the cell membrane of several cancers." (PMID 32927646, 2020).
tumor (continued). "In this study, we employ a poorly immunogenic MOC2-luc syngeneic tumor model and evaluate the efficacy of cancer-targeting CD44-targeted NIR-PIT." (PMID 33322807, 2020). "Among the known CSCs biomarkers, CD44 has unique features that make it one of the most promising tumor markers." (PMID 31973075, 2020). "In intracellular cytokine staining, we found more tumor infiltrating CD8+CD44+ T cells generating CD107 and Interferon-gama (IFNγ) in KO mice compared to WT mice when stimulated with PMA plus Ionomycin." (PMID 32477338, 2020). "While other biomarkers, such as CD44 and Nestin, were correlated with tumor staging, tumor size and lymph node metastasis." (PMID 31907037, 2020). "mEVs were loaded with doxorubicin (Dox) and decorated with hyaluronan (HA), in order to direct them to CD44-overexpressing tumor cells." (PMID 33271883, 2020). "Tumor tissue was homogenized to single cells; tumor cells were stained for markers CD44, CD133 and sorted using Fluorescence-activated cell sorting (FACS)." (PMID 33396774, 2020). "Compared with before NAC, the expressions of CD44, N-cadherin, β-catenin, and Vimentin in tumor tissues were significantly downregulated after NAC, while the expressions of E-cadherin and CD24 had no statistically significant change after NAC." (PMID 33282946, 2020). "In this study, both CTLA4 immune blockage alone and combination with CD44-targeted PIT increased the T cell infiltration into MOC1 tumor seven days after the treatments, suggesting that primary immune activation was augmented by CTLA4 immune blockade." (PMID 32937841, 2020). "Previous studies have shown that CD44 cells can act as tumor inducing cells promoting tumor transformation." (PMID 33372636, 2020). "Our study indicated that CD44 and autophagy proteins in tumor tissues of patients with recurrent NPC are higher than that of the relapse free patients." (PMID 32071548, 2020). "Further studies were performed to determine the effects of CD44 deletion on tumor cell survival in vitro and tumor growth in vivo." (PMID 32455980, 2020). "It appears therefore reasonable that palmitoylations can suppress the spread of tumor cells by keeping CD44 and the ERM adaptors in separate micro- or nano-domains of the membrane." (PMID 32271757, 2020). "CD44 is essential in the hematopoiesis process, tumor metastasis, lymphocyte activation, and MSC homing 10,11,22." (PMID 31929744, 2020). "To further clarify that CD44 cross-linking indeed regulates tumor cell migration and invasion by affecting p-Moesin in BrCas, we reduced Moesin expression in MDA-MB-231 and BT-549 by RNA interference." (PMID 33292278, 2020). "The HA receptor CD44 promotes cancer cell motility, tumor growth, angiogenesis as well as resistance to chemo- and radiotherapy, and is overexpressed in various tumors, including GBM." (PMID 32190011, 2020). "PKM2 cytoplasmic immunostaining was detectable in 167 out of 171 (97%) specimens, whereas CD44 membranous staining in 148 out of 172 (86%) tumor samples." (PMID 32326107, 2020). "CD44 participates in multiple physiological processes, and aberrant expression and dysregulation of CD44 contribute to tumor initiation and progression." (PMID 33303029, 2020). "Analysis of the T cells in the tumor-bearing mice showed that the percentage of CD44+CD62L− effector memory CD8+ T cells was greater for mice vaccinated with HM SNAs, when compared with admix treated group (p < 0.01)." (PMID 32733447, 2020). "CD24 positive tumors are reported to have a poor prognosis, and CD44 depletion has been shown to inhibit tumor proliferation and augment the effect of cytotoxic drugs." (PMID 33322363, 2020). "As expected, we found that CD44+/CD24−/low/EpCam+ MDA-MB-468 cells had higher tumor-initiating ability in this model." (PMID 32183150, 2020). "Ligands for the FR (e.g., folate) and CD44 (e.g., hyaluronic acid, CD44 antibodies) have been, therefore, widely used along with IONs for tumor targeting both in vitro and in vivo." (PMID 32932957, 2020).
tumor (continued). "CD25+CD44+ DN2 cells stained with an anti-BrdU detection antibody indicated that there was a modest decrease in total BrdU+ thymic cells in tumor progressors; however, proliferation amongst BrdU+ DN2 cells remained unchanged in control vs. tumor-bearing mice." (PMID 32582141, 2020). "These interactions are critical for CD44 function in cell–cell adhesion and cell motility related to inflammatory cell functions as well as in tumor growth and metastasis." (PMID 32679746, 2020). "After intravenous administration in tumor-bearing mice, CHA-rGO/Dox displayed higher tumor accumulation than rGO/Dox facilitating the cellular uptake of Dox by CD44-overexpressing tumor cells with enhanced anticancer effects." (PMID 32517278, 2020). "In summary, we describe a mechanism whereby CD44-expressing TMPs affect tumor cell metastatic characteristics by inhibiting cell adhesion properties." (PMID 33050539, 2020). "It has been reported that CD44 expression in tumor cells is regulated by transcription factors and miRNAs." (PMID 32168951, 2020). "Platelets adhere to tumor cells due to their expression of primary fibrinogen receptor αIIbβ3 integrin and P-selectin, which bind to CD44 and αvβ3 integrin on the surface of tumor cells." (PMID 33291452, 2020). "In fact, both CD44 mRNA and protein are highly expressed in the tumor tissues of patients with NSCLC." (PMID 32344833, 2020). "HA is a CD44-specific ligand which ensures that the EVs are directed to the cell membrane of the specified tumor cells." (PMID 33271883, 2020). "To obtain tumor-targeting peptides specific to U-87 MG cancer stem cells (CD44+/CD133+ cells), we screened the cyclic phage peptide library Ph.D.-C7C in vivo." (PMID 33396774, 2020). "We further showed tumourspheres/ALDH+CD44+ subsets from ascites-derived tumour cells/cell lines with CSC properties and enhanced glycolysis." (PMID 32390009, 2020). "We initially analyzed the mechanism of action of the combination vaccination by measuring the generation of CD44+ memory T cells in the tumor-infiltrating lymphocyte (TIL) population." (PMID 32547541, 2020). "We previously reported that CD44 expression was significantly upregulated in HCC tumor tissues of the same cohort." (PMID 32168951, 2020). "The folate receptor CD44 is highly expressed in a wide variety of tumor types and can be exploited for specific tumor targeting." (PMID 32532030, 2020). "Lewisx, Sox2, ALDH and CD44 expression, tumorsphere formation, resistance to 5-FU treatment and in vivo tumor growth were increased in FUT9-expressing MC38 cells compared to the control cells." (PMID 32927726, 2020). "The main ligand for CD44 is hyaluronic acid (HA), a major component of the extracellular matrix that is expressed by stromal and tumor cells." (PMID 31963556, 2020). "Next, CD44 expression was detected and assessed in PD-L1Negative and PD-L1Positive tumor tissues from GC patients." (PMID 33204322, 2020). "The binding of HA to CD44 promotes tumor cell growth in vivo by stimulating PI3K/Akt signaling pathway, which is known to stimulate cell survival." (PMID 32987767, 2020). "CD44 down-regulation strongly suppressed tumor cell growth in vivo, increased apoptosis, and reduced chemoresistance in hepatic CSC subpopulations when compared with the control group." (PMID 32987767, 2020). "This attribute was also preserved in TSC: cell density, the CSC marker CD44, and the necrotic fraction were highly dependent on the position and depth within the original tumor, as well as the distance to the formerly supplying vessels." (PMID 32560230, 2020). "Compared with the relapse free NPC patients, NPC patients with inside- field recurrence had higher levels of CD44 proteins in tumor tissues." (PMID 32071548, 2020). "A further illustration of how the gene expression level changed over time was made for CD36 and CD44 by plotting expression levels measured by NanoString against the time gap between primary and recurrent tumor samples." (PMID 33352957, 2020).